CRP (C-reactive protein)
Diseases named in the same sentence as CRP in open-access papers (continued):
Sharing a sentence is not in itself a finding about the gene and the disease.
lymph node metastasis (continued). "Univariate analysis for recurrence-free survival (RFS) showed that CRP/Alb ratio >0.089, carbohydrate antigen 19-9 (CA 19-9) >37 U/mL, lymph node metastasis, vascular invasion, and multiple tumors were significantly associated with postoperative recurrence." (PMID 32856868, 2020). "We have previously demonstrated that serum CXCL8 levels significantly correlated with CRP levels and the presence of lymph node metastasis in PC patients." (PMID 32867211, 2020). "Male patients, lymph node metastases, and higher tumor stage were related to elevated CRP level (OR = 1.67, 95% CI: 1.34‐2.09; OR = 2.40, 95% CI: 1.44‐3.99; OR = 1.39, 95% CI: 1.12‐1.74)." (PMID 33201589, 2020). "In this study, we found an elevated CRP was highly correlated with primary tumor status, tumor depth, and lymph node metastasis in OSCCs." (PMID 28209200, 2017). "The NLR (HR = 4.84, p = 0.007), CRP (HR = 10.06, p = 0.030), and the presence of pathological lymph node metastasis (HR = 4.73, p = 0.030) were correlated with significantly higher risks of death." (PMID 26944862, 2016). "In a multivariate analysis, the NLR (HR = 4.62, p = 0.030), CRP (HR = 10.80, p = 0.045), and pathological lymph node metastasis (HR = 12.35, p = 0.009) were also found to be significantly associated with OS." (PMID 26944862, 2016). "In consistent, our data also showed that the RGC patients with higher CRP level had larger tumor size (p = 0.004) and more Lymph node metastasis (p = 0.003)." (PMID 27303917, 2016). "CRP level predicts greater extent of tumor destruction including bone invasion, skin invasion, tumor status, and lymph node metastasis." (PMID 26292957, 2015). "Higher pre-treatment CRP level (CRP≥5.0 mg/L) was closely related with pathological tumor status (P<0.001), pathologic lymph node metastasis with ECS (P = 0.025), bone invasion (P<0.001), skin invasion (P<0.001) and tumor depth (>10 mm vs. ≤10 mm, P<0.001)." (PMID 25061977, 2014). "In the present study, CRP was found to be closely related to the recurrent primary tumor status, recurrent lymph node metastasis, distant metastasis, and recurrent tumor stage (P = 0.050, P = 0.007, P<0.001, and P<0.001, respectively)." (PMID 25061977, 2014). "This retrospective two-center study was initiated to evaluate the impact of CRP levels at diagnosis on lymph node metastasis in patients with penile cancer." (PMID 24148787, 2013). "Receiver operating characteristic (ROC) analysis showed that the AUC (95% CI) of the CRP value was 0.68 (0.51 – 0.85; p = 0.04) for lymph node metastasis at the time of penile surgery." (PMID 24148787, 2013). "The optimal CRP cut-off value to predict lymph node metastasis was set at 20 mg/l based on ROC analysis." (PMID 24148787, 2013). "Concerning lymph node metastases, 37 patients were in the normal group and 9 patients in the elevated CRP." (PMID 20673375, 2010). "Concerning lymph node metastases, 37 patients were in the normal group and 9 patients in the elevated CRP group." (PMID 20673375, 2010). "The MFP algorithm selected five prognostic factors as significant at the 5% level in a multivariable model: lymph node metastases, liver metastases, bone metastases, age, C-reactive protein and neutrophils." (PMID 16736003, 2006). "The MFP algorithm selected five prognostic factors as significant at the 5% level in a multivariable model: lymph node metastases, liver metastases, bone metastases, age, CRP and neutrophils." (PMID 16736003, 2006). "The incidence of liver metastases, peritoneal tumour deposits, lymph node metastases and intravascular invasion are higher in patients with elevated CRP levels." (PMID 15569387, 2004). "Elevated CRP levels could be indicative of a degree of skin or bone invasion, tumor status, and lymph node metastasis." (PMID 38910781, 2024). "Furthermore, serum CRP levels correlate with tumor size, clinicopathological characteristics, and lymph node metastasis." (PMID 39267838, 2024).
lymph node metastasis (continued). "In our case, lymphocyte–CRP and CRP–albumin ratios also changed and may therefore also predict lymph node metastasis in GBM." (PMID 37794336, 2023). "Furthermore, high levels of CRP can predict lymph node metastasis, advanced tumor stage, and recurrence in OC." (PMID 38071306, 2023). "The ICPI was significantly correlated with age, American Society of Anaesthesiologists Physical Status, white blood cell count, neutrophil count, lymphocyte count, monocyte count, platelet count, tumor diameter, tumor depth, lymph node metastasis, pTNM stage, operative procedure, and CRP." (PMID 36719281, 2023). "However, further cases are required to verify the prognostic ability of CRP in GBM with lymph node metastasis." (PMID 37794336, 2023). "Patients with the tumor limited to the intestinal wall (T1-4N0M0) had a 5.2-fold lower CRP concentration compared to patients with lymph node metastases (T1-4N+M0) and an almost 9-fold lower CRP concentration compared to patients with lymph node and distant metastases to the liver (T1-4N+M+)." (PMID 34441316, 2021). "Similarly, patients with elevated preoperative CRP were more likely to have extracapsular extension, seminal vesicle invasion, lymph node metastasis, positive surgical margins, and biochemical recurrence." (PMID 34512646, 2021). "The independent prognostic factors for OS, according to the multivariate analysis, were CRP/Alb ratio >0.089 (HR, 3.39; 95% CI, 1.72–6.67; p < 0.001); lymph node metastasis (HR, 2.82; 95%, CI 1.29–6.19; p = 0.01); and multiple tumors (HR, 2.70; 95% CI, 1.34–5.45; p = 0.005)." (PMID 32856868, 2020). "Higher CRP level was also found to be related with lymph node metastasis with ECS (P = 0.014)." (PMID 26292957, 2015). "CRP was elevated due to peri-tumor tissue destruction or lymph node metastasis." (PMID 26292957, 2015). "Recurrent primary tumor status (P = 0.035), recurrent lymph node metastasis (P = 0.003), high CRP level (≥5.0 mg/L) (P<0.001), high SCC-Ag level (≥2.0 ng/ml) (P = 0.001), and distant metastasis (P<0.001) were found to significantly influence OS after recurrence." (PMID 25061977, 2014). "Moreover, this analysis revealed an optimal CRP cut-off of 20 mg/l for predicting lymph node metastasis." (PMID 24148787, 2013). "The destruction of nearby tissue and lymph node metastasis is generally accompanied by tissue inflammation, and the infiltration of inflammatory cells and the production of cytokines, especially IL-6, increase the CRP level in the serum." (PMID 23383155, 2013). "Therefore, the aim of the current study was to investigate the significance of preoperative C-reactive protein (CRP) levels as a parameter for development of lymph node metastases or recurrence." (PMID 20673375, 2010). "Therefore, the aim of the current study was to investigate the significance of preoperative CRP levels as a parameter for development of lymph node metastases or recurrence." (PMID 20673375, 2010). "Based on our data set of 425 metastatic renal cell carcinoma patients, the MFP algorithm selected six prognostic factors as significant at the 5% level in a multivariable model: lymph node metastases, liver metastases, bone metastases, age, CRP and neutrophils." (PMID 16736003, 2006). "Therefore, we retrospectively assume that CRP may be a marker for lymph node metastasis in patients with glioblastoma." (PMID 37794336, 2023). "The present nomogram contains 6 variables (lymph nodes metastasis, liver metastasis, CA19-9, CEA, albumin, and CRP), all of which are commonly used in daily medical practice." (PMID 38057434, 2023). "In the setting of locally advanced and metastatic bladder cancer, both 6 and 12 month survival nomograms improved with the addition of CRP to traditional markers (age, ECOG, PS, Hb, LDH, visceral metastatic disease, and lymph node metastases)." (PMID 34512646, 2021).
lymph node metastasis (continued). "According to the univariate analysis, the CRP/Alb ratio >0.089, CA19-9 >37, lymph node metastasis, vascular invasion, and multiple tumors were significantly associated with postoperative recurrence." (PMID 32856868, 2020). "According to the univariate analysis, the CRP/Alb >0.089, CA19-9 >37, lymph node metastasis, vascular invasion, multiple tumors, and surgical margin positive were significantly associated with OS." (PMID 32856868, 2020). "The aim of this study was to evaluate the importance of CYFRA 21-1 and CRP as tumor markers in patients with OSCC at the time of initial diagnosis in correlation with tumor size, histologic grading, and lymph node metastasis." (PMID 26292957, 2015). "The levels of squamous cell carcinoma antigen (SCC-Ag) and C-reactive protein (CRP) can be used to predict tumor invasion, lymph node metastasis, staging and survival in patients with oral cavity cancer." (PMID 23383155, 2013). "Similarly, multivariate Cox proportional analysis for OS indicated that elevated CRP levels (p = 0.018), increased CEA levels (p = 0.023), and the existence of lymph node metastasis (p = 0.001) were independent prognostic factors." (PMID 38890157, 2024). "The backward elimination procedure in the Cox regression analysis identified 6 factors (lymph node metastasis, liver metastasis, carbohydrate antigen 19-9 [CA19-9; log scale], carcinoembryonic antigen [CEA; log scale], albumin, and C-reactive protein [CRP; log scale]) in the training set." (PMID 38057434, 2023). "Age, sex, albumin, pre-albumin, CRP, ferritin, CRP/Albumin ratio, tumor size, differentiation grade, lymph node metastases, perineural invasion, or vascular invasion were not statistically related with FR + CTC in our study." (PMID 38037003, 2023). "The group with a high CRP/albumin ratio (>0.085) had a higher clinical stage of TNM (p = 0.002) and larger primary tumors (p = 0.029) with statistically significant differences in lymph node metastasis and distant metastasis." (PMID 33066436, 2020). "Thus, high stromal and alveolar density of CD163+ TAMs significantly correlated with the C-reactive protein (CRP) level in circulation, the Ki-67 proliferation index and invasive size, tumor differentiation, lymph node metastasis and pathological stage." (PMID 33194645, 2020). "In OSCC patients with lymph node metastasis, the serum CYPFRA 21-1 and CRP could be useful in stratifying the patients." (PMID 26292957, 2015). "The levels of CRP correlated only with lymph node metastasis and not with tumour size and distant metastasis." (PMID 21294915, 2011). "The proportion of lymph node metastasis in the group of elevated CRP levels was smaller than that in the patients without CRP elevation." (PMID 20673375, 2010). "We also noted significant differences in serum CRP levels between patients with lymph node metastasis and those without lymph node metastasis (P = 0.024)." (PMID 19457231, 2009). "For example, consider a patient aged 50 years, with lymph node metastases but no liver and bone metastasis, CRP 23 mg l−1 and neutrophils 3000 (cells μl−1)." (PMID 16736003, 2006). "We retrospectively suggest that, in the absence of any signs of infection, increased CRP may indicate lymph node metastasis, even if the primary tumor is well controlled." (PMID 37794336, 2023). "This study demonstrates that high pre-NACRT mGPS and increased CRP/Alb ratio after NACRT are independent prognostic factors for patients with resectable or borderline resectable PDAC undergoing NACRT following pancreatic resection, like lymph node metastasis and cancer remnant." (PMID 33317455, 2020).
lymph node metastasis (continued). "We demonstrated that a low preoperative PNI value was associated with age, BMI, white and red blood cell counts, a large tumor size, deep invasion, lymph node metastasis, an advanced pStage, lower albumin concentrations, and higher C-reactive protein levels, but not preoperative serum CEA levels." (PMID 29534689, 2018). "However we noted significant differences in serum CRP levels between patients with lymph node metastasis and those without lymph node metastasis (r = 0.690, P = 0.000)." (PMID 21294915, 2011). "Studies have suggested that the combination C-reactive protein (CRP), systemic inflammation response index (SIRI) and PLR not only predicts OS, relapse-free survival (RFS), but also significantly correlates with the degree of lymph node metastasis in GC." (PMID 38511137, 2024). "Similarly, Aktekin’s group (2019) reported significantly raised CRP levels in irresectable vs reseactable PDAC, as well as in patients with radiological lymph node metastasis compared to node negative disease." (PMID 35020761, 2022).
bipolar disorder (85 papers, 2013 to 2026). A disorder of the brain that causes unusual shifts in mood, energy, activity levels and the ability to carry out day-to-day tasks. "Second, CRP level was more strongly associated with severe suicidal symptoms (MADRS item 10 score ≥4) than with mild suicidal symptoms or major affective disorder diagnosis." (PMID 39283831, 2024). "Elevated IL-6 and CRP levels have been associated with the pathophysiology of both unipolar and bipolar disorders, indicating systemic inflammation as a common characteristic in these conditions." (PMID 38785543, 2024). "Following outlier correction, there was evidence for a protective effect of CRP on risk of bipolar disorder (Outlier-Corrected IVW β=-0.03, SE=0.01)." (PMID 34280516, 2021). "For bipolar affective disorders, our findings were consistent with previous MR studies and epidemiological observations wherein elevated CRP was associated with an increased risk of bipolar disorders." (PMID 34386016, 2021). "The study showed a 1.21-fold increased risk for bipolar disorder with a 10% increase in genetically determined CRP levels." (PMID 29093685, 2017). "As for bipolar disorder, we found a nominal effect of a 1.21-fold increase in risk for bipolar disorder with a 10-s% increase in CRP level." (PMID 27327646, 2016). "Interestingly, we found that both poor impulse control and elevated levels of CRP were associated with the prominent suicidal symptoms among patients with major affective disorder." (PMID 39283831, 2024). "According to some studies, inflammation may be associated with weaker cognitive outcomes in bipolar disorder, and high CRP has been associated with some low cognitive indices in this group of patients." (PMID 37933420, 2023). "In addition, they found a nominally significant association (an association that needs to be confirmed) between genetically increased CRP levels and an increased risk of knee osteoarthritis, raised diastolic and systolic blood pressure, and bipolar disorder." (PMID 27327646, 2016). "The findings also provide preliminary evidence that genetically raised levels of CRP may be causally associated with an increased risk of raised blood pressure, knee arthritis, and bipolar disorder." (PMID 27327646, 2016). "Though this nominal predisposing effect needs to be confirmed, our finding corroborates epidemiological observations suggesting that elevated CRP is associated with the disease and supports a potential causal influence of general inflammation in bipolar disorder." (PMID 27327646, 2016). "Previous evidence has suggested that elevated pro-inflammatory cytokines and/or CRP partially explain severity of cognitive impairment, but several other constructs, not always adjusted for, are known to influence inflammation and be associated with bipolar disorder." (PMID 36043690, 2021). "Individuals with bipolar disorder presented significantly higher levels of CK-MB (p = 0.0016), CRP (p < 0.0001), IL-6 (p = 0.0198), and IL-1β (p = 0.0067)." (PMID 41750331, 2026). "The aim was to investigate cognitive subgroups in patients with bipolar disorder and their association with serum levels of BDNF and CRP." (PMID 41367212, 2025). "The largest cluster is “inflammation” (#0, size: 331), followed by clusters of “cytokines” (#1, size: 322), “neuroinflammation” (#2, size: 321), “c-reactive protein” (#3, size: 314), “bipolar disorder” (#4, size: 278), “gut microbiota” (#5, size: 197)." (PMID 39791171, 2025). "In bipolar depression, the intricate relationship of zinc, albumin, IL-6, and CRP with the symptoms assessed using the HAMD-17 and MADRS scales reveals a more complex interaction." (PMID 38785543, 2024). "Both unipolar and bipolar disorders exhibit similar profiles in key inflammatory markers, IL-6 and CRP." (PMID 38785543, 2024). "Our study indicated the distinct effects of major affective disorder diagnosis and suicide symptom severity on inhibitory control function and CRP and TNF-α levels." (PMID 39283831, 2024).